HDAC2 (histone deacetylase 2)
Diseases named in the same sentence as HDAC2 in open-access papers (continued):
Sharing a sentence is not in itself a finding about the gene and the disease.
infection (23 papers, 2008 to 2025). The state of being infected such as from the introduction of a foreign agent such as serum, vaccine, antigenic substance or organism. "Increased promoter recruitment of p50, HDAC1, HDAC2 and Sirt1 to the NF-kB-associated site A region of the mir-424-503 gene was found in cells following infection, as assessed by ChIP analysis using primers covering the NF-kB-binding region within the promoter." (PMID 23724129, 2013). "The co-immunoprecipitation (Co-IP) assay further verified the interaction between FOXO3 and HDAC2 in wild type (WT) macrophages, while this association was weakened upon Pg inoculation, but restored under KDP136 infection." (PMID 40404630, 2025). "To demonstrate the IAV-induced STAT3 nuclear translocation and the role of HDAC1 and HDAC2 in such translocation, we used an early infection timepoint, 6 h." (PMID 39861822, 2024). "Of note, there was an additional upper band (denoted with star) detected by the HDAC2 antibody in cells after infection for 24 and 36 h." (PMID 34445287, 2021). "Protein synthesis was dramatically increased either by infection of Ad-HDAC2 WT (3rd column) or Ad-HDAC2 S394E (5th column)." (PMID 30050113, 2018). "Ad-HDAC2 S394E successfully increased HPG incorporation despite the infection of Ad-PPP2CA (6th column), whereas Ad-HDAC2 WT failed to overcome the suppression of PPP2CA (4th column)." (PMID 30050113, 2018). "We found that there was a statistically non-significant 24.7% and a significant 47.3% (P = 0.02) decrease in HDAC2 polypeptide levels in infected cells after 12 and 24 h of infection, respectively." (PMID 28769891, 2017). "We found that when normalized to GAPDH, the infection of A549 cells with PR8 at an MOI of 0.5 and 5.0 caused a significant 40% (P = 0.0001) and 61.3% (P = 0.0001) reduction in HDAC2 mRNA level, respectively." (PMID 28769891, 2017). "A further knockdown in HDAC2 expression by up to 90% via RNA interference augmented the growth kinetics of IAV in A549 cells by more than four-fold after 24 h of infection." (PMID 28769891, 2017). "After 24 h of infection, cells were processed to measure the HDAC2 mRNA level by quantitative real-time PCR (qPCR)." (PMID 28769891, 2017). "HDAC2 knockdown significantly decreased cell viability at day 3 (P<0.05), day 4 (P<0.01), and day 5 (P<0.001) after infection." (PMID 28538837, 2017). "We found that the level of HDAC2 polypeptide (∼60 kDa) in WSN-infected cells decreased with the progress of infection, peaking at 24 h; whereas, it remained largely unchanged throughout in uninfected cells." (PMID 28769891, 2017). "We found that, like WSN, infection with PR8 also reduced the HDAC2 polypeptide level in A549 cells, and in a dose-dependent manner." (PMID 28769891, 2017). "A noticeably decreased levels of pSTAT1 were detected in the cells transfected with HDAC2 siRNA compared to the cells transfected with control siRNA after 6 and 12 h of infection." (PMID 28769891, 2017). "Viperin was barely detectable in HDAC2 siRNA-transfected cells after 12 h of infection, and after 24 h of infection, it was detected at a reduced level compared to the control siRNA-transfected cells." (PMID 28769891, 2017). "To delineate the transcript level of HDACs during MTB infection, we measured the levels of HDAC1 and HDAC2 expression in human macrophages following infection." (PMID 26697414, 2015). "ASFV promotes H3K9me3 and HP1β foci formation from early infection, followed by HP1α and HDAC2 nuclear enrichment, suggesting heterochromatinization of host genome." (PMID 26389938, 2015). "Gene expression analysis of HDAC1 and HDAC2 in A. phagocytophilum-infected cells by qRT-PCR showed a transient increase in HDAC1 expression that peaked within 24 hours post-infection, whereas HDAC2 transcription steadily increased over time." (PMID 19543390, 2009).
infection (continued). "Expression of several histone deacetylases was also regulated during infection: HDAC2 and HDAC10 expression levels increased, while HDAC3, HDAC6, and HDAC9 expression decreased." (PMID 18331636, 2008). "Likewise, IAV also antagonizes HDAC1 and HDAC2, and their levels are decreased in infected cells at the later infection timepoints." (PMID 39861822, 2024). "In this study, the expression of lncRNA-11496 was decreased after infection with T. gondii, which may have less binding to HDAC2, resulting in increased expression of HDAC2 in the brain." (PMID 32499679, 2020). "HDAC2 knockdown or control BMM‐transferred mice were challenged with intact gram‐negative E. coli to further assess the effect of HDAC2 on the host macrophage‐mediated innate response to pathogen infection." (PMID 30207412, 2019). "Infection of bronchial epithelial cells results in increased histone deacetylase 2 (HDAC2) that appears to alter innate immune responses; inhibition of HDAC2 results in increased production of type I IFN and decreased viral replication both in cultured cells and following RSV infection of mice." (PMID 29515570, 2018). "Likewise, when normalized to GAPDH, the infection with WSN at an MOI of 0.5 and 5.0 caused a significant 40.6% (P = 0.0001) and 60.6% (P = 0.0001) reduction in HDAC2 mRNA level, respectively." (PMID 28769891, 2017). "Furthermore, a significant 1.9-fold (P = 0.02) increase in intracellular NP level in HDAC2-depleted cells compared to control cells was also observed after 24 h infection by WB." (PMID 28769891, 2017). "After infection with E. coli, markedly reduced serum TNF‐α and IL‐12p70 levels were observed in HDAC2 knockdown BMM‐transferred mice compared with their control littermates." (PMID 30207412, 2019). "Such visualization at later infection timepoints could have skewed the results and the effect of HDAC1 and HDAC2 on IAV-induced STAT3 nuclear translocation." (PMID 39861822, 2024). "After 12 and 24 h of infection, the cells with depleted expression of HDAC2 released a statistically non-significant 2.6-fold and a significant 4.2-fold (P < 0.0001) more infectious progeny, respectively, than the control cells at the corresponding times." (PMID 28769891, 2017). "To quantify the decrease in pSTAT1 and viperin levels in the absence of HDAC2, we repeated this experiment at least two more times and quantitated their levels at 12 h of infection." (PMID 28769891, 2017). "Since PML interacted with STAT1, STAT2, HDAC1, and HDAC2, we investigated whether IE1 simultaneously interacts with PML, STAT1, STAT2, and HDACs during infection." (PMID 25812002, 2015). "In the absence of infection, phosphorylation is an established regulator of HDAC1 and HDAC2 activity and protein associations." (PMID 23807710, 2013). "The related histone deacetylases, HDAC2 and HDAC6, failed to associate with viral DNA after infection." (PMID 20846395, 2010). "Therefore, the visualization of STAT3 nuclear translocation in the presence or absence of HDAC1 or HDAC2 expression at the 6 h infection timepoint represents its accurate activation window." (PMID 39861822, 2024). "In co-IP assays performed at 8 h after infection, PML was found to interact with STAT1, STAT2, HDAC1, and HDAC2 in UV-HCMV-infected cells but not in uninfected cells." (PMID 25812002, 2015). "Next, A549 cells transfected with either non-targeting control siRNA or HDAC2-targeting siRNA were infected with WSN at an MOI of 0.5, and the culture medium and the infected cells were separately harvested after 2, 6, 12, and 24 h of infection." (PMID 28769891, 2017). "Infection of HepG2 cells with recombinant lentiviruses expressing Prox1-targeting siRNA precursors lenti-si258 or lenti-si1646 effectively knocked down endogenous Prox1 expression, without markedly affecting LSD1 or HDAC2 expression." (PMID 23626788, 2013).
neurodegenerative disease (18 papers, 2014 to 2025). A disorder of the central nervous system characterized by gradual and progressive loss of neural tissue and neurologic function. "In models of neurodegenerative diseases, it has been found that pharmacological inhibition of HDACs or HDAC2 silencing prevent histones hypoacetylation and increase gene expression, in addition to rescuing or reducing cognitive deficit." (PMID 38635564, 2024). "Hdac2 knockdown restores cognition in a mouse model of AD and histone deacetylase inhibitors have been proposed as neurodegenerative disease therapeutics." (PMID 37328865, 2023). "HDAC2 inhibition has been reported to increase synaptic plasticity in neurodegenerative disease models." (PMID 32811822, 2020). "HDAC2 has been shown to play an important role in neurodegenerative diseases, including AD, by inducing an epigenetic blockade on expression of genes involved in synaptic plasticity and cognition." (PMID 29579087, 2018). "Kinetically selective HDAC2 inhibitors rescued the memory deficits in mice with neurodegenerative disease by increasing H4K12 and H3K9 histone acetylation in hippocampal neurons." (PMID 27536989, 2016). "Based on these results, focus on the role of HDAC2 in neurodegenerative diseases has increased." (PMID 31024248, 2019). "Therefore, the application of selective HDAC2 inhibitors could have strong therapeutic implications in the treatment of neurodegenerative diseases." (PMID 39682714, 2024). "Human induced pluripotent stem cell-derived neurons (hiPSC-Ns) are widely used models for studying neurodegenerative disease mechanisms, but the role of HDAC2 in hiPSC-N differentiation and maturation has not been explored." (PMID 33802405, 2021). "Previous studies have demonstrated that HDAC2 expression is specifically increased in neurons in the AD brain using immunohistochemical approaches and HDAC inhibition may have therapeutic potential for neurodegenerative disease." (PMID 33802405, 2021). "Moreover, our observations that Tip60 HAT/HDAC2 imbalance and concomitant transcriptional dysregulation occur early during neurodegenerative progression, such HAT based therapeutics may be effective for early and general neurodegenerative disease protection." (PMID 33106538, 2020). "Indeed, albeit HDAC2 and HDAC6 could represent promising drug targets in AD, it remains unknown which drug or dosing regime present the most efficacy, and similar conclusions can be drawn for other neurodegenerative diseases." (PMID 25071843, 2014).
adenocarcinoma (6 papers, 2008 to 2025). A common cancer characterized by the presence of malignant glandular cells. "Furthermore, our examination of the TCGA database demonstrated a positive association between YY1 and HDAC2 expression in both lung and adenocarcinoma tissues." (PMID 37495623, 2023). "Strong nuclear HDAC1, HDAC2 and HDAC3 immunoreactivity was seen in most adenocarcinomas." (PMID 18212746, 2008).
inflammation (5 papers, 2018 to 2025). Aberrant reaction of the microcirculation characterized by movement of fluid and leukocytes from the blood into extravascular tissues. "Thus, we speculate that the HDAC2 inhibitor may indirectly alleviate pancreatic inflammation in rats by improving molecular changes in the spinal cord." (PMID 40337468, 2025).
neurological disorders (5 papers, 2017 to 2022). "in addition, several animal models of neurological disorders are also evident to have increased HDAC2 levels in brain samples." (PMID 35877665, 2022). "The authors identified distinct hot spots in highly homologous HDAC1 and HDAC2 that shed light on the development of specific HDAC2 inhibitors against neurological diseases." (PMID 29594101, 2018). "Our data support the idea that manipulation of HDAC2 may be beneficial in the treatment of neurological diseases." (PMID 33802405, 2021).
hematological cancers (3 papers, 2015 to 2022). "Histone deacetylase 2 (HDAC2) is overexpressed or mutated in several disorders such as hematological cancers, and plays a critical role in transcriptional regulation, cell cycle progression and developmental processes." (PMID 25473896, 2015). "HDAC2 is crucial for embryonic development, affects cytokine signaling involved in immune responses, and is often highly up-regulated in solid and hematological tumors." (PMID 25473896, 2015).
neurodevelopmental disorder (3 papers, 2020 to 2024). A behavioral and cognitive disorder with onset during the developmental period that involves impaired or aberrant development of intellectual, motor, or social functions. "In addition, molecular investigation of this HDAC2 variant could represent preliminary findings for disclosing pathogenetic mechanisms underlying this neurodevelopmental disorder affecting the epigenetic machinery." (PMID 38753158, 2024). "In contrast, individuals suffering from Alzheimer’s and neurodevelopmental disorders(Like ASD) showed the higher HDAC2 level in brain samples." (PMID 35877665, 2022).
hematological disorders (2 papers, 2016 to 2020). "This provides the rationale for utilization of selective Hdac1 and Hdac2 inhibitors in the treatment of hematological malignancies." (PMID 27886239, 2016). "The two histone deacetylases (Hdacs), Hdac1 and Hdac2, are erasers of acetylation marks on histone tails, and are important regulators of gene expression that were shown to play important roles in hematological malignancies." (PMID 27886239, 2016).
kidney diseases (2 papers, 2017 to 2023). "VPA (inhibitor of HDAC1 and HDAC2), which was used in the clinic for many years, has been found to play a protective effect on a variety of kidney diseases." (PMID 37153759, 2023).
peripheral neuropathies (2 papers, 2022). "A recently published experiment revealed that HDAC2 suppression enhanced the EAAT2 and VGLUT2 expression following paclitaxel-induced Peripheral Neuropathy." (PMID 35877665, 2022).
cardiovascular diseases (1 paper, 2025). "HDAC2 (Histone Deacetylase 2) is involved in vascular smooth muscle cell (VSMC) phenotypic switching, proliferation, and migration, contributing to cardiovascular diseases." (PMID 39981435, 2025).
heart diseases (1 paper, 2024). "For example, histone acetyltransferase (HAT) p300 is upregulated in heart diseases, and inhibition of histone deacetylase 2 (HDAC2) induces a hypertrophic signal." (PMID 38406555, 2024).
HDAC2 also shares sentences with these, for which no sentence is quoted: benign tumors (3 papers); chronic pancreatitis (3); hypertrophy (3); acute promyelocytic leukemia (2); airway hyperresponsiveness (2); cholangiocarcinoma (2); Duchenne muscular dystrophy (2); endometrial cancer (2); Hodgkins lymphoma (2); kidney (2); metabolic disorders (2); nephrotic syndrome (2); oral squamous cell carcinoma (2); Thrombocytopenia (2); adenovirus infection (1); airway allergy (1); alcohol use disorder (1); alcoholism (1); amyotrophic lateral sclerosis (1); anaphylaxis (1); anaplastic thyroid cancer (1); angioimmunoblastic T-cell lymphoma (1); Arrhythmia (1); Arthritis (1); astrocytomas (1); ataxia telangiectasia (1); bladder tumors (1); brain disorder (1); Burkitt lymphoma (1); calcific aortic valve disease (1).
A further 72 diseases each share a sentence with HDAC2 in 1 paper.